SPRTN (SprT-like N-terminal domain)
Description:
DNA-dependent metalloendopeptidase that mediates the proteolytic cleavage of covalent DNA-protein cross-links (DPCs) during DNA synthesis, thereby playing a key role in maintaining genomic integrity. DPCs are highly toxic DNA lesions that interfere with essential chromatin transactions, such as replication and transcription, and which are induced by reactive agents, such as UV light or formaldehyde. Associates with the DNA replication machinery and specifically removes DPCs during DNA synthesis. Catalyzes proteolytic cleavage of the HMCES DNA-protein cross-link following unfolding by the BRIP1/FANCJ helicase. Acts as a pleiotropic protease for DNA-binding proteins cross-linked with DNA, such as TOP1, TOP2A, histones H3 and H4. Mediates degradation of DPCs that are not ubiquitinated, while it is not able to degrade ubiquitinated DPCs (By similarity). SPRTN activation requires polymerase collision with DPCs followed by helicase bypass of DPCs (By similarity). Involved in recruitment of VCP/p97 to sites of DNA damage. Also acts as an activator of CHEK1 during normal DNA replication by mediating proteolytic cleavage of CHEK1, thereby promoting CHEK1 removal from chromatin and subsequent activation. Does not activate CHEK1 in response to DNA damage. May also act as a 'reader' of ubiquitinated PCNA: recruited to sites of UV damage and interacts with ubiquitinated PCNA and RAD18, the E3 ubiquitin ligase that monoubiquitinates PCNA. Facilitates chromatin association of RAD18 and is required for efficient PCNA monoubiquitination, promoting a feed-forward loop to enhance PCNA ubiquitination and translesion DNA synthesis.
Synonyms: DVC1; Spartan; C1orf124; DKFZP547N043; PRO4323
Tractability: Small molecule: a structure with a bound ligand is known. PROTAC: UniProt records ubiquitination sites on it; ubiquitination databases record sites on it.
Gene: Protein-coding gene on chromosome 1 (231,337,104 to 231,355,023, forward strand). Ensembl gene ENSG00000010072.
Subcellular location: Nucleus; Chromosome
Subcellular location (Human Protein Atlas): Nucleoplasm
Pathways (Reactome):
DNA Repair: Translesion Synthesis by POLH
Gene Ontology:
Molecular function: double-stranded DNA binding; K63-linked polyubiquitin modification-dependent protein binding; metalloendopeptidase activity; protein binding; single-stranded DNA binding; ubiquitin binding; polyubiquitin modification-dependent protein binding; DNA binding
Biological process: DNA damage response; interstrand cross-link repair; positive regulation of protein ubiquitination; protein autoprocessing; protein-DNA covalent cross-linking repair; proteolysis; response to UV; translesion synthesis; DNA repair
Cellular component: chromatin; chromosome; nuclear speck; nucleoplasm; nucleus
Genetic constraint (gnomAD): Loss-of-function variants: 11 observed, 34.3 expected, observed/expected ratio (o/e) 0.32, 90% interval 0.2 to 0.53. The upper end of that interval is the gene's LOEUF score, 0.53, which puts it in group 2 of 6, group 1 being the genes least tolerant of losing a copy. Missense variants: 482 observed, 622.62 expected, observed/expected ratio (o/e) 0.77, 90% interval 0.72 to 0.83. Synonymous variants: 185 observed, 226.26 expected, observed/expected ratio (o/e) 0.82, 90% interval 0.72 to 0.92.
Homologues: Orthologues: chimpanzee SPRTN (99% identical), macaque SPRTN (97% identical), dog SPRTN (83% identical), rabbit SPRTN (80% identical), pig SPRTN (78% identical), rat Sprtn (72% identical), guinea pig SPRTN (72% identical), mouse Sprtn (72% identical), zebrafish sprtn (43% identical), tropical clawed frog sprtn (43% identical), Drosophila melanogaster mh (35% identical), Caenorhabditis elegans dvc-1 (32% identical).